CTLA4 (cytotoxic T-lymphocyte associated protein 4)
Diseases named in the same sentence as CTLA4 in open-access papers (continued):
Sharing a sentence is not in itself a finding about the gene and the disease.
tumor (continued). "Taking CD4+ Treg cells and CD8+ cytotoxic T cells as examples, Treg cells derived from tumor tissues showed higher expression of LAYN, LGALS1 and TNFRSF1B, and cytotoxic T cells derived from tumor tissues showed higher expression of TNFRSF9 (encoding 4-1BB), LAYN and CTLA4." (PMID 36104333, 2022). "The relationship between CRGs-related risk score and immune checkpoints also suggested that calcium may play a suppressive role in the anti-tumor immune responses due to the negative association with PD-1, CTLA-4, and other inhibitory immune checkpoints." (PMID 36588677, 2022). "Thus, we postulated that different tumor pyroptosis regulation patterns might be crucial in determining immunotherapy response against PD-1/PD-L1 or CTLA-4." (PMID 35274175, 2022). "However, CTLA-4 has the same functional expression on tumor and T cells." (PMID 36358874, 2022). "To determine if knocking out apoE in tumor cells induced immunogenicity, we vaccinated wild type and apoE-/- mice or wild type and lrp8-/- mice with WT B16 or apoE-/- B16 tumor cells and CTLA4 Ab and then collected splenocytes from these vaccinated mice 6 days later." (PMID 36341364, 2022). "Beyond the effect on tumor intrinsic pro-inflammatory pathways, a series of recent investigations demonstrate the involvement of DNA methylation in regulating the expressions of multiple immune checkpoint molecules like PD-L1, PD-L2, CTLA-4, LAG3, TIM-3, and Galectin-9." (PMID 35693795, 2022). "Among the 6 immune checkpoints, CTLA4, CD86, and PDCD1LG2 were highly expressed in the high-risk group (Wilcoxon rank-sum test, p < 0.05), suggesting that these genes may serve as key targets for anti-tumor therapy in CRC." (PMID 35719389, 2022). "In addition, Au/Ag NRs-induced PTT and PDT sensitized tumors to the anti-CTLA-4 antibody to trigger a long-term immune memory, leading to the inhibition of the lung metastasis of the 4T1 tumors and the protection of mice against tumor cell rechallenge 40 days post treatment." (PMID 35630880, 2022). "Moreover, combining the anti-PD-1 mAb and anti-CTLA-4 mAb administration enhanced the RT-induced distant antitumor effects involved in the accumulation of HER2-tumor antigen-specific CD8-positive T cells at HER2-positive tumor sites." (PMID 35763240, 2022). "Previous studies have shown that the interaction between tumor cells and CAR T cells may trigger the expression of immunosuppressive factors (such as cytotoxic T-lymphocyte-associated antigen 4 [CTLA-4] and programmed cell death protein 1 [PD-1]) resulting in T-cell exhaustion or dysfunction." (PMID 36618357, 2022). "In addition, tumor immune escape may be caused by upregulation of tumor cell infiltrating immune cells (TIICs) or their ligands at suppressive immune checkpoint in CRC, such as PD-1, PD-L1 and CTLA-4." (PMID 36177034, 2022). "Therefore, it can also be selectively used in tumor tissues with anti-CTLA-4 antibodies." (PMID 36588722, 2022). "We also identified therapy-associated upregulation of several immune checkpoints including CTLA-4, PD-1, and Tim-3, which may reflect acute T-cell activation, but also underscores the potential for subsequent T-cell exhaustion/dysfunction and tumor immune escape." (PMID 35440655, 2022). "Hence, anti-tumor responses and signals may also upregulate inhibitory genes and signaling pathways such as IFNγ, CTLA-4, and PD-L1 in immune cells." (PMID 36142818, 2022). "One is to promote tumor antigen recognition and presentation, such as using GM-CSF, toll-like receptor agonists; The other is to eliminate the immunosuppressive factors in the tumor microenvironment, mainly by using immune checkpoint inhibitors, such as CTLA-4 inhibitors and PD-1/PD-L1 inhibitors." (PMID 35198442, 2022).
tumor (continued). "Interestingly, while subcutaneous tumors exhibited higher levels of immune-inhibiting checkpoint cytotoxic T-lymphocyte associated protein 4 (CTLA-4) and PD-1 on T cells as compared to orthotopic tumors, these tumors persisted post α-PD-1 and α-CTLA-4 treatment while orthotopic tumor growth ceased." (PMID 35736351, 2022). "However, preclinical evidence suggests that depletion of Tregs or abrogating their function may be the main contributor to the anti-tumor activity of CTLA-4 blockade." (PMID 35326731, 2022). "Besides, Treg cells constitutively express CTLA-4 that further restrains anti-tumor immunity." (PMID 35898507, 2022). "Cytotoxic T lymphocyte-associated antigen-4 (CTLA-4), also known as CD152, is a membrane protein expressed on CD4+ and CD8+ T cells that is involved in the downregulation of T cell immune response at the tumor site upon interaction with CD80/B7.1 and CD86/B7.2 on APC." (PMID 35625811, 2022). "However, when combined with radiation therapy, anti-CTLA-4 antibody treatment provoked both tumor regression and T cells to stop on tumor cells (so increasing contact time and favoring tumor cell killing) in an MHC-I and NKG2D-mediated manner, in line with the in vitro data." (PMID 35681548, 2022). "We found that cluster 1 had the highest levels of expression in PD1, PDL1, PDL2, and CTLA4, indicating that high expression of immune checkpoint inhibitors in cluster 1 patients may form an immunosuppressive microenvironment, further leading to tumor escape." (PMID 36421781, 2022). "Hence, anti-CTLA4 inhibitors can potentially be used to activate T cells and kill tumor cells." (PMID 36042469, 2022). "Particularly, it has been shown that anti-CTLA-4 may inhibit T-regulatory cells and promote relative effector cell expansion, whereas the addition of RT enhances the diversity of clonal T-cell expansion, resulting in enhanced tumor regression in animal models." (PMID 35440655, 2022). "Nevertheless, human PDACs are highly resistant to anti‐PD1 or anti‐cytotoxic T lymphocyte‐associated antigen‐4 (CTLA4)‐based immunotherapy except a few microsatellite‐unstable cases, suggesting that SMAD4 loss alone could be insufficient to promote tumor response to checkpoint blockade." (PMID 35064757, 2022). "Additionally, combining eganelisib with both anti-CTLA4 and anti-PD-1 therapy results in CR rates of 30% in breast and 80% in melanoma models (B16-GM-CSF) and provided immunity to tumor re-implantation, whereas dual checkpoint inhibition alone did not result in any complete responses." (PMID 36031601, 2022). "Interestingly, MSS/CD8+ CRCs were characterized by an upregulation of seven immune signatures (TIS, IFN gamma signaling, MHC2, CD45, CTLA4, and PD-L2) and overexpression of tumor-intrinsic responses such as APM and the signature measuring key components of the immunoproteasome." (PMID 36010943, 2022). "Moreover, tumor immunity could be triggered by blocking the pathways of PD-1/PD-L1/CTLA-4, while the immunity to infection could be inhibited." (PMID 34992611, 2021). "A clinical study using IM in combination with the CTLA-4 inhibitor Ipilimumab in 10 patients with advanced GISTs showed that 9 patients (8 with mutations in KIT exon 11 and 1 with a mutation in KIT exon 13) all progressed, but in 1 case of WT GIST, the tumor shrank by 68%." (PMID 34956906, 2021). "The increase in richness of the TCR repertoire in the periphery of anti-CTLA-4 treated patients, suggested to result from unleashed T-cell priming, could be expected to enhance immune control of the tumor through the generation of new T cell responses covering a broader range of neoantigens." (PMID 33602280, 2021). "This inhibitory effect might potentially occur through the interaction between CTLA-4 expressed by the tumor cells and B7 ligands expressed by the tumor microenvironment cells including the antigen presenting cells (APC), such as dendritic cells (DCs), or antitumor activated T cells." (PMID 33906311, 2021).
tumor (continued). "Intertumoral application of NDV-ICOSL in bilateral flank tumor models caused increased infiltration of activated T cells in virus-injected and remote tumors resulted in a satisfactory rejection of the tumors when of the combinative form of NDV-ICOSL and systemic CTLA-4 blockade was utilized." (PMID 34267616, 2021). "This analysis confirmed the NanoString expression data and showed that tumor-infiltrating human lymphocytes expressed high levels of PD-1, T-cell immunoglobulin and mucin-domain containing-3 (TIM-3), cytotoxic T-lymphocyte-associated protein-4 (CTLA-4) and lymphocyte-activation gene-3 (LAG-3)." (PMID 33589524, 2021). "Under chronic stimulation of tumor antigens, CD8+ T cells are progressively exhausted, which is related to a unique transcription program that up-regulates the expression of T cell surface inhibitory receptors (IRs) such as PD-1 and cytotoxic T lymphocyte-associated protein-4 (CTLA-4)." (PMID 34036867, 2021). "We next tested if anti-CTLA-4 ICI therapy in combination with IRE could improve tumor control." (PMID 34162858, 2021). "Additionally, combination of tumor ablation with checkpoint inhibitors like anti-CTLA4 could enhance anti-tumor immunity in vivo, too." (PMID 33805268, 2021). "The scarcity of effector T cells in the tumor is compounded by enrichment of regulatory T cells (Treg), a subpopulation of CD4+ T cells that suppress effector T cells through cytotoxic T lymphocyte–associated protein 4 (CTLA-4) signaling and secretion of cytokines TGF-β and interleukin-10." (PMID 33496872, 2021). "In line with the usage of PARPi in DDR-deficient tumors, PARPi combined with immune checkpoint blockade, including PD-1/PD-L1 and CTLA-4, exerts remarkable efficacy in tumors with BRCA1/2 or ERCC1 mutations via STING-dependent immune responses and infiltration of cytotoxic T cells into tumor." (PMID 34970273, 2021). "Indeed, tumor cells can upregulate cytotoxic T lymphocyte antigen (CTLA)-4 or programmed death ligand 1 (PD-L1), which can inhibit T cells by competing with the stimulatory signal of CD28 and by triggering inhibitory receptor programmed cell death 1 (PD1), respectively." (PMID 33535559, 2021). "Therefore, CTLA-4 inhibitors facilitate immune-mediated anti-tumor response by antagonizing CTLA-4/B7 interactions, enabling CD28/B7 costimulatory interactions, and subsequently leading to direct activation and expansion of effector T cells which can target cancer antigens." (PMID 33946408, 2021). "Some potential predictive biomarkers have been identified up to now, such as tumor mutational burden (TMB), mismatch repair deficiency (dMMR), immune cell infiltration, and inhibitory receptors related gene expression such as PD-1, PD-L1, CTLA-4, LAG-3, TIM3, and TIGIT." (PMID 34367952, 2021). "In the TCV setting, the systemic administration of an anti-CTLA-4 monoclonal antibody may provide not only enhanced expansion of spontaneously primed T cells in the tumor-draining lymph node, but also vaccine-induced T cells in the lymph node draining the vaccination site." (PMID 34290704, 2021). "However, recently additional mechanisms have been proposed to explain the immunotherapeutic effect of anti-CTLA-4 mAbs including Fc receptor-dependent depletion of regulatory T (Treg) cells in tumor microenvironment, and blocking of trans-endocytosis of B7 on dendritic cells (DC)." (PMID 34531847, 2021). "Our study implies that CD80 expression on tumor cells should be evaluated further as a possible predictive marker that may assist clinicians in the selection of cancer patients who may be suitable for CTLA-4 blockade cancer therapy." (PMID 33923750, 2021). "Moreover, radiotherapy can increase tumor PD-L1 expression, MHC I expression, exhaustion of CD8+ T cells and changes in the tumor microenvironment, which may enhance the resistance to anti-CTLA-4 and anti-PD-L1/PD-1." (PMID 33922480, 2021).
tumor (continued). "Screening for onco-proteomic sEV-based biomarkers in HNSCC provided the first evidence that immunoregulatory proteins such as PD-1, PD-L1, and CTLA-4 can be utilized as markers of tumor progression and might play an important functional role due to their immunosuppressive effects." (PMID 34439329, 2021). "Furthermore, there is inverse association between positive and high CTLA4 expression in tumor cells and negative and low expression in lymphocytes (P= 0.001 and 0.000 respectively for positivity and 0.005 and 0.009 respectively for high score of expression)." (PMID 33906311, 2021). "Additionally, sodium ascorbate (vitamin C) has been shown to decrease tumor growth in a T-cell-dependent manner, enhance T cell infiltration into the tumor mass, potentiate clinical efficacy of immune checkpoint therapy with anti-PD-1 and anti-CTLA-4 monoclonal antibodies in murine BC models." (PMID 34885122, 2021). "Therefore, joint blocking of CTLA-4 and PD-1 signal transduction pathway may be an effective way to rescue immunosuppression of malignant tumors including glioma and maintain anti-tumor immune response." (PMID 34630121, 2021). "Immune checkpoint blockade reestablishes the anti-tumor response and prevents tumor cells from evading immune surveillance by targeting specific molecules such as programmed death receptor 1 (PD-1) or its ligand (PD-L1) and cytotoxic T lymphocyte antigen 4 (CTLA-4)." (PMID 34290608, 2021). "However, T cells activated by anti-PD-1/PD-L1 or anti-CTLA-4 may be inhibited by other immunosuppressive cells or factors in the tumor immune microenvironment." (PMID 33716732, 2021). "Additionally, we also found that CD58 might act as an immune checkpoint gene in HCC via PD1/CTLA4 pathways and regulate the levels of tumor-infiltrating immune cells in HCC tissues, which might be an immunotherapeutic target in HCC." (PMID 34423049, 2021). "The risk score did not correlate with levels of PD-1, PD-L1, CTLA4, or tumor mutational burden." (PMID 34925311, 2021). "Many types of tumours that were considered untreatable only a few years ago currently show promising clinical response rates upon treatment with biologicals, such as monoclonal antibodies targeting so-called immune check-point inhibitors (ICIs), like PD-1/PD-L1 and CTLA-4." (PMID 35052732, 2021). "This may indicate the important role of CTLA-4 action in regulating anti-tumor responses." (PMID 35083014, 2021). "Furthermore, our data suggest that it is possible that CD80, CD86, and the CTLA-4-dependent tumor immune escape is involved in the development of tumor aggressiveness, a hypothesis that also merits further study." (PMID 34745002, 2021). "NC410 showed decreased tumor growth as a monotherapy, but it might even show better clinical efficacy when used in combination with currently used checkpoint receptor inhibitors such as CTLA4 and/or PD-1." (PMID 34121658, 2021). "Furthermore, the combination of anti-PD-L1 + anti- cytotoxic T lymphocyte associated protein 4 (CTLA-4) leads to both increased survival times and induces long-term tumor regression in 50% of the population, featuring acquired resistance to cancer re-challenge." (PMID 34553039, 2021). "However, unlike IL-10 and TGF-β1 mRNA, Ctla-4 transcripts were largely eliminated at 12 days such that at later timepoints, one would expect a diminution of cell surface CTLA-4 and subsequent diminution of Treg inhibition of effector cell clearance of tumor cells." (PMID 34375938, 2021). "Similarly, E7046, an orally bioavailable EP4-specific antagonist, also showed synergistic antitumor activity when combined with anti-CTLA-4 antibodies through impairing tumor-promoting MDSCs differentiation, M2 macrophage polarization, and Tregs-derived immunosuppression." (PMID 35003065, 2021).
tumor (continued). "Similarly, PTT using the organic nanocomposite PLGA-ICG-R837 combined with anti-CTLA4 exerted significant suppressive effects on primary and distant tumors, followed by the generation of memory T cells and inhibition of tumor recurrence and long-term tumor-free survival." (PMID 34068491, 2021). "Systemic treatment with antibodies can trigger effects on tumor cells (over-) expressing designated surface antigens, like the epidermal growth factor receptor (EGFR), programmed cell death protein 1 (PD-1), its ligand (PD-L1), as well as the cytotoxic T lymphocyte-associated protein 4 (CTLA-4)." (PMID 34884998, 2021). "Thus, anti-CTLA-4 treatment promotes the expansion of T cells, including tumor-reactive T cells." (PMID 34112740, 2021). "In addition, tumor cells may express inhibitory immune checkpoints, such as CTLA4 and PD-L1, which may inhibit the cytolytic effect of effector T cells activated by DCs, providing a rationale for the use of combination therapy." (PMID 34885150, 2021). "Thus, CTLA-4 may play a role in tumor metastasis, especially that of CRC, by affecting immune cell function and cytokine secretion, but this role might not be significant in other tumors, as it may be masked by some unknown factors." (PMID 34367975, 2021). "Briefly, mTOR could regulate the expression of cytokines/chemokines, including interleukin-10 (IL-10) and transforming growth factor-β (TGF-β), and/or membrane receptors, such as cytotoxic T-Lymphocyte protein 4 (CTLA-4), PD-L1 and PD-1, to modulate tumor immune cells." (PMID 34458019, 2021). "Radiation increased the clonality and divergence of T cell receptor (TCR) repertoire when used in combination with anti-CTLA-4, suggesting a diverse TCR repertoire is required to achieve tumor rejection and may underlie the synergy between radiotherapy and CTLA-4 blockade." (PMID 34078406, 2021). "For example, the anti-tumor function of CD8 + T cells may be inhibited via the exhaustion of T cells, and after CTLA-4 blockade in glycolysis-low tumors, the functional destabilization of Treg cells towards interferon-γ-producing cells may promote anti-tumor immunity." (PMID 34417437, 2021). "Bacteroides was reported to enhance the anti-CTLA-4 therapy’s efficiency and restore the its effects after an administration of antibiotics through a proposed mechanism involving the activation of the IL-12-dependent Th1 cells with cross-reactivity to tumor and bacterial antigens." (PMID 34203292, 2021). "In addition, pulse MEK treatment combined with CTLA-4 blockade can prolong the survival time of KRAS-mutant tumour in mice, which may be related to T cell activation and increased CTLA-4 expression due to MEK pulse therapy." (PMID 34012925, 2021). "CTLA-4 inhibitors go to the source and increase the anti-cancer T-cell numbers, while PD-1 inhibitors act in peripheral blood or tumors, allowing the binding process of PD-1 to PD-L1 to be blocked in these viable agents, thus freeing ICs to kill and launch a strike against the tumor." (PMID 34541363, 2021). "Another study was conducted to test whether the relationship between the response to CTLA-4 monoclonal antibodies and the gut microbiome was the same as that in anti-PD1 therapy and it was found that Bacteroidales play a key role in the effects of tumour immunity induced by the blockade of CTLA-4." (PMID 34412621, 2021). "Human IgGs from four of these collections (i.e., PD-1, PD-L1, Lag-3 and CTLA-4), were characterized and found to specifically bind to their targets with high affinity, to efficiently activate T cell proliferation, to induce cytokine secretion and inhibit in vivo tumor growth." (PMID 34201082, 2021). "Treatment with anti-CTLA-4 antibody could deplete Tregs in tumor microenvironment in mice." (PMID 34194437, 2021).